SRPK1 (SRSF protein kinase 1)
Diseases named in the same sentence as SRPK1 in open-access papers (continued):
Sharing a sentence is not in itself a finding about the gene and the disease.
tumor (73 papers, 2006 to 2026). "By identifying differential splice variants and disrupted pathways, we aimed to uncover SRPK1-driven splicing events with potential relevance to tumor biology and therapeutic targeting." (PMID 41551143, 2025). "SRPK1 is implicated in the promotion of each of the hallmarks of cancer across one tumour type or another." (PMID 35583632, 2022). "It has been reported that knockdown of SRPK1 and inhibition of SRPK1 prevented angiogenesis and was associated with tumor growth through regulating the alternative splicing of VEGF." (PMID 35846993, 2022). "SRPK1 activity has been associated to increased tumor cell proliferation, migration and angiogenesis in different cancers." (PMID 33287867, 2020). "In stomach cancer, high SRPK1 was also found compared to the normal stomach histology and was associated with higher grade, stage, larger tumor size, lymph node metastases, and shorter overall survival." (PMID 31861708, 2019). "Among the A3SS loci in C33A, STOML2 (overexpressed and prognostic in CCa) and BDNF-AS (tumor-suppressive in CCa) illustrate that SRPK1-associated splice-site alterations may occur in genes relevant to CCa." (PMID 41551143, 2025). "However, previous studies have primarily focused on the splicing activity of SRPK1, with few studies assessing its function as a scaffold oncoprotein during tumor progression and the underlying mechanisms." (PMID 36869126, 2023). "SRPK1 knockdown was associated with decreased cell proliferation and reduced tumour growth in vivo." (PMID 35583632, 2022). "Numerous pre-clinical studies investigating a host of different tumour types; have found increased SRPK1 expression to be associated with proliferation, invasion, migration and apoptosis in vitro as well as tumour growth, tumourigenicity and metastasis in vivo." (PMID 35583632, 2022). "Taken together, SRPK1 plays an important role in tumor-associated pathway activation, which might enhance drug-resistance." (PMID 34193174, 2021). "In addition, specific inhibition of SRPK1 in a mouse tumor model has been shown to be associated with reduced tumor growth." (PMID 31151317, 2019). "Importantly, the protein expression level of SRPK1 was positively associated with the tumor stage (P<0.001)." (PMID 28977917, 2017). "Studies have shown that SRPK1 exhibits oncogenic effects in various tumor types and regulates the PI3K/AKT signaling pathway." (PMID 41141389, 2026). "Comparative evidence in other tumour models demonstrated that inhibiting SRPK1 changes the splice-site selection in VEGF165 (pro-angiogenic isoforms)." (PMID 41551143, 2025). "The C33A response highlights a tumor-specific mechanism whereby SRPK1 inhibition maintains protein homeostasis instead of initiating death." (PMID 41551143, 2025). "The analysis revealed that risk genes (BOP1, CTBP1, DSE, SRPK1, and PMSD10) were significantly upregulated in tumor samples, whereas the protective gene HACD4 was highly expressed in normal samples." (PMID 40963856, 2025). "By integrating both single-cell and bulk RNA-seq data, we identified six key prognostic genes (BOP1, CTBP1, DSE, PMSD10, SRPK1, and HACD4), which were associated with poor prognosis and tumor cell proliferation." (PMID 40963856, 2025). "The increasing number of SRPK1 transcripts accounted for the higher average in tumors when compared with non-tumor adjacent." (PMID 41403742, 2025). "The identification of prognostic markers through Cox regression and Lasso regression further highlighted the significant role of the risk genes BOP1, CTBP1, DSE, SRPK1, and PMSD10, which were upregulated in high mRNAsi tumor cells." (PMID 40963856, 2025). "The activity of SRPK1 is closely related to the expression and function of various tumor-related genes, including EGFR (epidermal growth factor receptor), VEGF (vascular endothelial growth factor), and others." (PMID 38397980, 2024).
tumor (continued). "The results indicated a significant decrease in tumorigenic ability after SRPK1 knockout compared with the control group, as evidenced by a reduction in subcutaneous tumor volume and weight." (PMID 38397980, 2024). "Subcutaneous tumor transplantation experiments in nude mice also showed that silencing SRPK1 significantly reduced the tumorigenic ability." (PMID 38397980, 2024). "Now that we had found that METTL3 targets SRPK1 and promotes tumour growth in LUAD, the mechanism by which SRPK1 influenced LUAD progression was further explored." (PMID 39095708, 2024). "SRPK1 also regulates cell proliferation, apoptosis, and invasion in a variety of tumor cell types, thereby influencing oncogenesis." (PMID 38702316, 2024). "T2-weighted MRI (magnetic resonance imaging) analysis revealed a significantly smaller intracranial tumor volume in SRPK1-shRNA cells compared with normal tumor cells." (PMID 38397980, 2024). "We demonstrated that STM2457 also had an anti-tumour effect in SRPK1-overexpressing LUAD xenograft tumours, which was also one of the first research where STM2457 was applied in LUAD xenograft models." (PMID 39095708, 2024). "The results showed that overexpression of SRPK1 significantly promoted tumour growth while application of STM2457 abrogated the additional growth." (PMID 39095708, 2024). "SRPK1 can act as a tumour suppressor by forming a complex with active AKT1 and the PHLPP1 phosphatase (alongside chaperones), which together inactivate AKT by dephosphorylating key regulatory sites." (PMID 37607329, 2023). "Understanding the mechanisms that underpin both activities in human tumours will be important for effective targeting of SRPK1 by cancer therapeutics." (PMID 36895328, 2023). "The relationship between SRPK1 expression and sensitivity or resistance to cisplatin-containing chemotherapy appeared to be tumor/cell specific." (PMID 36303126, 2022). "Overexpression of wild-type SRPK1 promoted HCC cell proliferation while forced expression of its kinase-dead mutant or silencing SRPK1 resulted in attenuated tumor growth both in vitro and in vivo." (PMID 35192432, 2022). "Here, we first demonstrated that SRPK1 was upregulated in CESCs on both mRNA and protein levels, and its upregulation was remarkably correlated with tumor progression as well as unfavorable prognosis." (PMID 35192432, 2022). "Over the last decade, SRPK1 has been reported as both tumor suppressor and promoter, depending on the cellular context and has been implicated in both chemotherapy sensitivity and resistance." (PMID 35719374, 2022). "For example to date there is limited data regarding how SRPK1 expression is influenced by external factors such as the tumour microenvironment." (PMID 35583632, 2022). "Inhibition of this signalling pathway via introduction of a chimeric antibody targeting SRPK1 activity has been found to inhibit cell growth, migration and invasion in vitro and tumour growth in vivo." (PMID 35583632, 2022). "SRPK1 expression is also closely related to the response of various tumours to platinum-based chemotherapeutic agents." (PMID 35583632, 2022). "Though SRPK1 is generally found to be highly expressed in these tumours, SRPK1 downregulation correlated positively with cisplatin resistance and poor prognosis in this study." (PMID 35583632, 2022). "Nevertheless, more and more studies are now focusing on developing SRPK1 inhibitors to test the tumor-suppressing functions." (PMID 35192432, 2022). "Further investigation into the contribution of various factors within the tumour microenvironment towards SRPK1 activity are warranted." (PMID 35583632, 2022). "On the contrary, increasing SRPK1 in tumor phosphorylates SRSF1 and stimulates its nuclear import, which favors the splicing at the proximal splice site of VEGF pre-mRNA and leads to the expression of the VEGFxxx isoform and neovascularization." (PMID 36140826, 2022).
tumor (continued). "Here, we demonstrated that SRPK1 was upregulated in CESCs on both mRNA and protein levels, and its upregulation was remarkably correlated with tumor progression as well as unfavorable prognosis." (PMID 35192432, 2022). "Considering that specific effect of kinase is largely depend on its substrate, identification of other SRPK1 substrates will be invaluable for further illustrating its tumor-related role." (PMID 33602301, 2021). "Among the four groups, SRPK1&2-overexpressing group showed the highest proliferation capacity and largest tumor size." (PMID 33602301, 2021). "SRPK1 is involved in tumor growth in case of several cancers and considered to be among attractive targets for the development of anti-cancer therapeutic compounds." (PMID 33291073, 2020). "Our data showed that SRPK1 was associated with alternative splicing of CHK1 in both cancer cells and tumor tissues." (PMID 32194790, 2020). "Knockout of WT1 in tumor endothelium decreased SRPK1 and SRSF1 expression and shifted VEGFA splicing toward the production of the anti-angiogenic VEGF-A120 isoform." (PMID 33287867, 2020). "Liver cancer was also characterized by SRPK1 overexpression, while the latter was correlated with higher stage, larger tumor size, and shorter survival." (PMID 31861708, 2019). "SRPK1 reduced expression—induced either through gene knockdown or the SRPK1 inhibitor SPHINX—suppressed angiogenesis thus tumor growth in vivo through a switch in VEGF alternative splicing." (PMID 31861708, 2019). "Investigation with SRPK1 knocked-down cell lines showed a shift towards the anti-angiogenic VEGF165b isoform, while xenografts showed decreased tumor growth and decreased MVD in tumors." (PMID 31151317, 2019). "SPHINX31, a specific inhibitor of SRPK1, promoted the same splicing switch in favor of VEGF165b and inhibited tumor growth in vivo." (PMID 31134126, 2019). "Wt1, Srpk1, Srsf1, and the angiogenic VEGF164a isoform were highly expressed in tumor endothelium compared to normal lung endothelium." (PMID 30641926, 2019). "In the case of the GTPase Rac1 (Ras-related C3 botulinum toxin substrate 1), it resulted in the expression of the isoform Rac1b which sustains tumor survival; SRPK1 downregulation was tumor suppressive through downregulating the expression of Rac1b." (PMID 31861708, 2019). "We show here that Wt1, Srpk1, Srsf1, and the angiogenic Vegf 164a isoform are highly expressed in tumor endothelial cells compared to normal lung endothelium." (PMID 30641926, 2019). "We show that, in tumor endothelium, Wt1, Srpk1, and Srsf1 are upregulated compared to normal lung endothelium." (PMID 30641926, 2019). "SPHINX is the latest generation SRPK1 inhibitor; it exhibits anti-tumour effects after repetitive intraperitoneal administration in a mouse model of orthotopic PCa." (PMID 29693622, 2018). "One such protein, SR-protein kinase 1 (SRPK1), is overexpressed in various human cancers including breast and correlates with tumor progression and invasiveness." (PMID 30241319, 2018). "For instance, SRPK1 is regarded as the molecular determinant of tumor cell migration and cancer metastasis." (PMID 28678795, 2017). "Here we investigated the expression pattern of SRPK1 in GC by immunohistochemistry and found that it was up-regulated in tumor tissues, where its expression was correlated with tumor grade and prognosis." (PMID 28977917, 2017). "Several studies further identified that inhibition of SRPK1 showed tumor-suppressive effects, thus raising SRPK1 as a novel candidate chemotherapy target." (PMID 28977917, 2017). "Statistical analyzes revealed that SRPK1 high expression was correlated with advanced tumor stage and poor prognosis." (PMID 28977917, 2017). "The expression of SRPK1 was significantly higher in tumour compared with benign tissue, with a median difference in expression score of 2 (IQR 1–3, p<0.00001, Mann–Whitney test)." (PMID 26500332, 2016).
tumor (continued). "SRPK1 expression was significantly higher in tumour compared with benign tissue (p<0.00001) and correlated with higher pT stage (p=0.004), extracapsular extension (p=0.003) and extracapsular perineural invasion (p=0.008)." (PMID 26500332, 2016). "Increased SRPK1 expression in breast and colonic cancer has been coordinately correlated to the enhancement of tumor grade." (PMID 26273588, 2015). "Our results that SRPK1 also regulates cell migration and tumorigenic potential invitro suggest that some tumor suppressor genes, oncogenes and/or cell adhesion molecules are targets of SRPK1-mediated splicing events and other transcriptional processes." (PMID 23236423, 2012). "According to tumor cell migration screening, SRPK1 is essential for breast cancer metastasis." (PMID 40032844, 2025). "Inhibition of SRPK1 holds promise in hindering tumor growth and metastasis." (PMID 39083441, 2025). "BUB3, DHFR, RRM1, and SRPK1 were also expressed in immune cells of GC's tumor microenvironment." (PMID 39895799, 2025). "Such disparities highlight how the oncogenic effects of SRPK1 activity differ by tumour type." (PMID 41551143, 2025). "Additionally, in this study, we established a xenograft mouse model and confirmed the role of SRPK1 in the tumor growth of xenografts in mice." (PMID 38397980, 2024). "We confirmed several of our DSGs in mouse tumours, including Hnrnpa1, Srpk1, Hnrnpc, and Mlx." (PMID 39313128, 2024). "In splicing-dependent machinery, SRPK1 regulates multiple splicing and leads to tumor progression." (PMID 37342192, 2023). "The inhibition and knockdown of the SR splice factor kinase SRPK1 reduces tumour growth in vivo." (PMID 36895328, 2023). "Furthermore, during tumor angiogenesis, SRPK1 maintains the balance between the expression of the pro-angiogenic vascular endothelial growth factor (VEGF)-A165 and the anti-angiogenic VEGF-A165b." (PMID 36869126, 2023). "Additional investigations concerning the spacer domain of SRPK1 will improve our understanding of tumor progression and help to determine whether SRPK1 represents a viable therapeutic target in gefitinib-resistant NSCLC patients." (PMID 36869126, 2023). "Moreover, SRPK1, the most-studied member of SRPKs, has been reported to function as both an oncogene and tumor suppressor depending on its expression level." (PMID 35719374, 2022). "Our findings on the tumor-suppressing role by SRPK1-knockdown may provide novel insights for CESC research and guidance for individual therapy." (PMID 35192432, 2022). "SRPK1 activity appears to be highly specific and sensitive to variations in tumour biology." (PMID 35583632, 2022). "Xenograft models were utilized to verify tumor-related roles of SRPK1/2 and PP1α in vivo." (PMID 33602301, 2021). "As a result, SRPK1&2 group showed the highest Ki-67 staining percentage, while PP1α-T320A group and sh-SRPK1/2 group showed decreased Ki-67 level, which is consistent with tumor growth curve." (PMID 33602301, 2021). "Finally, the tumor-related role of SRPK1/2, SRSF1, Mnk2b, and PP1α were validated in CAC cell lines as well as in xenograft models." (PMID 33602301, 2021). "Furthermore, higher SRPK1 was observed in patients with larger tumor size and advanced tumor stages." (PMID 33602301, 2021). "One explanation for the increase in SRPK1 levels in HPV-infected cells could be that these cells represent tumour progression." (PMID 32182205, 2020). "Increased levels of SRSFs and SRPK1 have been detected in tumour cells." (PMID 32182205, 2020). "SRSF1 mRNA levels were unaltered upon siRNA or drug inhibition of SRPK1 in HPV-infected keratinocytes (data not shown), suggesting that SRSF1 may undergo proteasomal degradation in the cytoplasm of SRPK1-depleted, or inhibited, non-tumour keratinocytes." (PMID 32182205, 2020). "We analyzed VEGF isoforms, Wt1, Srpk1, and Srsf1 in normal and tumor endothelium." (PMID 30641926, 2019).
tumor (continued). "Inhibition of Srpk1 and Srsf1, and alterations in Vegf splicing, which induce tumor endothelial cell apoptosis, might contribute to the antitumor activity upon targeting Wt1." (PMID 30641926, 2019). "Except for NSCLC cells, SRPK1 acts on the endothelial cells of the tumor microenvironment." (PMID 31861708, 2019). "To summarize, SRPK1 downregulation affects both tumor epithelial cells and endothelial cells of the microenvironment, whilst it suppresses the acquisition of CSC phenotype, migration, invasion, metastasis, and angiogenesis and promotes apoptosis in preclinical NSCLC models." (PMID 31861708, 2019). "Therefore, we determined VEGF isoforms, Wt1, Srpk1, and Srsf1 expression in normal and tumor endothelial cells." (PMID 30641926, 2019). "Of these, SRPK1 has been shown to have a tumor-suppressive effect and is a candidate driver gene." (PMID 31160636, 2019). "For example, when the tumor suppressor SRPK1 (serine/arginine-rich splicing factor kinase), which mediates the recruitment of the phosphatase PHLPP1 to Akt (besides its role in regulated splicing) was deleted or overexpressed, it resulted in the promotion of cancer." (PMID 30577430, 2018). "SRPK1 inhibitors decrease tumour growth in a PCa mouse model in vivo providing strong evidence that they could be used therapeutically for treating PCa." (PMID 29693622, 2018). "Interestingly, SRPK1 plays tumor suppressing role in mouse embryonic fibroblasts, on that SRPK1-silencing induces cell transformation." (PMID 28977917, 2017). "Taking into consideration that SRPK1 was an important kinase, we then wanted to test whether its kinetic activity was indispensable in tumor promoting." (PMID 28977917, 2017). "Subsequent SRPK1 knockdown appeared to suppress metastasis to distant organs, and to inhibit focal adhesion reorganization, suggesting that its activity and function are fundamental to tumour cell migration in this particular cancer type 13." (PMID 27859253, 2017). "Indeed, a recent study reported highly potent, selective, and cell active SRPK1 inhibitors, which also have antiangiogenic properties in vivo, shedding light on its novel anti-tumor applications." (PMID 28977917, 2017). "Besides ERK and AKT, SRPK1 can activate several other tumor-related proteins in distinct tumor types, such as JNK and VEGFs." (PMID 28977917, 2017). "Finally, in a therapeutic proof-of-principle experiment we have shown that intraperitoneal administration of a specific SRPK1 inhibitor (SPHINX) is able to reduce tumour growth in an orthotopic mouse model of PCa." (PMID 26995304, 2016). "First, only selected samples of tumour were analysed for SRPK1 expression." (PMID 26500332, 2016). "Moreover, knockdown of SRPK1 in a colon carcinoma cell line decreased tumour growth and microvessel density." (PMID 26995304, 2016). "Interestingly, it has been demonstrated that depending on the context SRPK1 can act as either oncogene or tumor suppressor." (PMID 26273588, 2015). "SRPK1 presented tumor suppressor activity since its inactivation in mouse embryonic fibroblasts could induce cell transformation." (PMID 26273588, 2015). "However, the mean relative fold expression of the SRPK1 protein was significantly different between tumor samples and normal samples (independent samples t-test, p-value = 0.03)." (PMID 23236423, 2012). "However, the level of the human SRPK1 gene has been both positively and negatively correlated with resistance of tumor cells to treatment regimens containing platinum." (PMID 23236423, 2012). "Recently, it has been shown that SRPK1 is overexpressed in tumors of the pancreas, breast, and colon and siRNA-mediated down-regulation of SRPK1 in tumour cell lines results in a dose-dependent decrease in proliferative capacity and increase in apoptotic potential." (PMID 16919171, 2006). "Novel anti-tumor drugs targeting SRPK1 may be developed in the future." (PMID 38397980, 2024).